FBLN1 (fibulin 1)
Description:
Incorporated into fibronectin-containing matrix fibers. May play a role in cell adhesion and migration along protein fibers within the extracellular matrix (ECM). Could be important for certain developmental processes and contribute to the supramolecular organization of ECM architecture, in particular to those of basement membranes. Has been implicated in a role in cellular transformation and tumor invasion, it appears to be a tumor suppressor. May play a role in haemostasis and thrombosis owing to its ability to bind fibrinogen and incorporate into clots. Could play a significant role in modulating the neurotrophic activities of APP, particularly soluble APP.
Synonyms: FBLN; FIBL1
Tractability: Antibody: its Gene Ontology location is reachable by antibodies, with high confidence; UniProt places it where antibodies can reach, with medium confidence; UniProt predicts a signal peptide or a membrane-spanning region. PROTAC: ubiquitination databases record sites on it.
Gene: Protein-coding gene on chromosome 22 (45,502,238 to 45,601,981, forward strand). Ensembl gene ENSG00000077942.
Subcellular location: Secreted, extracellular space, extracellular matrix
Subcellular location (Human Protein Atlas): Endoplasmic reticulum; Predicted to be secreted
Pathways (Reactome):
Extracellular matrix organization: Molecules associated with elastic fibres
Gene Ontology:
Molecular function: calcium ion binding; extracellular matrix structural constituent; fibrinogen binding; fibronectin binding; identical protein binding; integrin binding; protein binding; protein-containing complex binding; peptidase activator activity
Biological process: blood coagulation, fibrin clot formation; integrin-mediated signaling pathway; negative regulation of cell adhesion; negative regulation of cell motility; negative regulation of ERK1 and ERK2 cascade; negative regulation of protein phosphorylation; negative regulation of stem cell proliferation; negative regulation of substrate adhesion-dependent cell spreading; embryo implantation; extracellular matrix organization
Cellular component: elastic fiber; extracellular exosome; extracellular matrix; extracellular region; non-collagenous component of interstitial matrix; basement membrane
Genetic constraint (gnomAD): Loss-of-function variants: 34 observed, 91.03 expected, observed/expected ratio (o/e) 0.37, 90% interval 0.28 to 0.5. The upper end of that interval is the gene's LOEUF score, 0.5, which puts it in group 2 of 6, group 1 being the genes least tolerant of losing a copy. Missense variants: 774 observed, 999.53 expected, observed/expected ratio (o/e) 0.77, 90% interval 0.73 to 0.82. Synonymous variants: 391 observed, 392.83 expected, observed/expected ratio (o/e) 1, 90% interval 0.92 to 1.08.
Homologues: Orthologues: macaque FBLN1 (97% identical), dog FBLN1 (91% identical), pig FBLN1 (87% identical), rat Fbln1 (86% identical), mouse Fbln1 (85% identical), chimpanzee FBLN1 (85% identical), guinea pig FBLN1 (84% identical), tropical clawed frog fbln1 (58% identical), rabbit FBLN1 (57% identical), zebrafish fbln1 (54% identical), Caenorhabditis elegans fbl-1 (34% identical). Paralogues in human: FBLN2 (44% identical), EYS (26% identical), EFEMP2 (23% identical), FBLN5 (22% identical), EFEMP1 (21% identical), VWDE (19% identical).
Diseases named in the same sentence as FBLN1 in open-access papers:
FBLN1 is named in the same sentence as 165 diseases in open-access papers, as found by Europe PMC text mining. Sharing a sentence is not in itself a finding about the gene and the disease. The quoted sentences say what the papers report.
breast carcinoma (35 papers, 2003 to 2025). "It functions as a tumor suppressor in prostate cancer and breast cancer, and the inactivation of FBLN1 has been linked to the progression of gastric cancer." (PMID 40433364, 2025). "Overexpressed variants of FBLN1 play a crucial role in estrogen-induced carcinogenesis in ovarian and breast cancers." (PMID 39201719, 2024). "Fbln-1 has been implicated as having a role in cancer, especially in breast carcinoma, and possible involvement in triggering protective antitumor immune responses." (PMID 21113302, 2010). "Taken together, these findings indicate that elevated expression and altered processing of fibulin-1 is associated with human breast cancer." (PMID 12644824, 2003). "The present investigation demonstrates that elevated fibulin-1 protein expression is associated with breast cancer." (PMID 12644824, 2003). "Assuming that the observed immunoreactive polypeptides correspond to proteolytic fragments of fibulin-1, our results indicate that altered proteolysis of fibulin-1 is also associated with breast cancer." (PMID 12644824, 2003). "However, fibulin-1 expression in the stroma is associated with increased malignancy in ovarian and breast cancers." (PMID 31508361, 2019). "In this study, we indicate that altered fibulin-1 processing is associated with breast cancer." (PMID 12644824, 2003). "As processing was associated with both ERα and PR in human breast carcinomas, we next studied the relation of fibulin-1 processing in vitro using three ER/PR-positive (MCF-7, T47D and BT-474) and three ER/PR-negative (MDA-MB-231, HS-578-T and SK-BR-3) human breast tumour-derived cell lines." (PMID 12644824, 2003). "Of note, Fbln2 had significant positive correlations with Fbln1 and Fbln5 in all breast cancer subtypes." (PMID 39110274, 2024). "Silencing of fibulin-1 has shown an increment in cell proliferation in MCF-7 in vitro, and a low proliferation index was found in fibulin-1-expressing breast cancer tissue samples." (PMID 37719007, 2023). "Fibulin-1 has previously shown the ability to inhibit cell migration, invasion, and motility in melanoma, epidermoid carcinoma, and breast carcinoma cell lines through inhibition of ERK activation based on fibronectin-specific mechanisms." (PMID 37719007, 2023). "In this study, BM genes with differential expression and prognostic correlation in breast cancer were selected as promising prognostic biomarkers for breast cancer, including FBLN1, FBLN5, ADAMTS8, LOXL1, SDC1 and PXDNL." (PMID 37056938, 2023). "Based on the TCGA-BRCA dataset, we found that LOXL1, SDC1 and PXDNL were highly expressed in breast cancer while the expressions levels of FBLN1, FBLN5 and ADAMTS8 were lower than those in normal breast samples." (PMID 37056938, 2023). "One study shows that overexpression of FBLN-1 in breast cancer cell lines promotes resistance to doxorubicin, whereas another study reports that inhibition of FBLN-1 in cancer cell lines increases the sensitivity to the same drug." (PMID 36361532, 2022). "The tumor-suppressing role of FBLN1 has been described in many types of cancers like gastric carcinoma, prostate cancer, breast cancers, and ovarian cancers." (PMID 35127942, 2022). "On the other hand, an increased expression of fibulin-1 has been found in the sera of breast cancer patients, suggesting its role in the progression or pathogenesis of breast cancer." (PMID 34063320, 2021). "Increased fibulin 1 and ECM1 have been associated with different malignancies, and, in cases of breast cancer, it was shown to elicit a TH2 response." (PMID 35386989, 2021). "In contrast, the interaction of fibulin-1 with ADAMTS-1 in breast cancer cell lines induces an anticancer effect." (PMID 34063320, 2021). "In a recent study, the interaction between fibulin-1 and ADAMTS-1 was associated with antitumor effects in breast cancer cell lines." (PMID 31508361, 2019).
breast carcinoma (continued). "The two mCAF markers Fibulin-1 and PDGFRα identified a profuse infiltration of mCAFs in the tumor stroma of human breast cancer tissue." (PMID 30514914, 2018). "On the other hand, breast cancers exhibit elevated fibulin-1 expression compared with surrounding normal tissue, implicating fibulin-1 as a promoter of breast cancer development and progression." (PMID 30227601, 2018). "It has been shown that fibulin-1 mediates chemo-resistance in breast cancer cells and furthermore seems to play pivotal roles in cancer immuno-surveillance." (PMID 27270657, 2016). "The plasma fibulin-3 and fibulin-1 levels were elevated in patients with mesothelioma and breast carcinoma, respectively." (PMID 25885889, 2015). "We have shown for the first time that FBLN1 is upregulated in breast cancer cell lines treated with T3." (PMID 24587767, 2014). "With use of SEREX, serum AAbs to the glycoprotein Fbln-1 were identified in 15/20 (75%) breast carcinoma patients compared to 4/20 (25%) healthy controls (P < .0006)." (PMID 21113302, 2010). "It has been concluded that the SEREX-defined molecule Fbln-1 is able to elicit both cellular and humoral immune responses in breast carcinoma patients." (PMID 21113302, 2010). "Fibulin 1 overexpression is correlated with better prognosis in breast cancer, and FBLN1 is downregulated in prostate cancer cells." (PMID 18985039, 2008). "Current evidence suggests that FBLN1 plays a tumour suppressive role not only in gastric cancer but also in other cancers such as breast cancer and prostate cancer." (PMID 18985039, 2008). "This 50-set also contains genes previously linked to breast cancer prognosis, metastasis or treatment response (BCL2, CXCL12 and FBLN1)." (PMID 19094230, 2008). "The level of mature fibulin-1 polypeptide (100 kDa) was higher in the breast carcinoma specimens as compared to normal breast tissue (Mann–Whitney U-test, P=0.0005)." (PMID 12644824, 2003). "Fibulin-1 protein expression was significantly increased in breast carcinomas as compared to normal breast tissue (Mann–Whitney U-test, P=0.0005)." (PMID 12644824, 2003). "Fibulin-1 has been shown to suppress the adhesion and motility of a number of tumour cell lines, including the breast carcinoma cell line MDA-MB-231." (PMID 12644824, 2003). "In this study, fibulin-1 protein expression in breast carcinoma specimens and normal breast tissue was evaluated immunohistologically." (PMID 12644824, 2003). "Fibulin-1 protein expression was semiquantitatively assessed in a range of breast carcinoma and normal breast tissue biopsies by densitometric analysis of immunoblots." (PMID 12644824, 2003). "In conclusion, our results have shown that fibulin-1 protein is elevated in human breast carcinomas as compared to normal breast tissue." (PMID 12644824, 2003). "Specifically, a 50 kDa N-terminal fragment of fibulin-1 was detected more frequently in breast carcinomas as compared to normal breast tissue." (PMID 12644824, 2003). "This work is in agreement with a recent study showing increased expression of fibulin-1 mRNA in a small panel of breast carcinoma specimens as compared to normal breast tissue." (PMID 12644824, 2003). "Much of what we know about fibulin 1 with respect to breast cancer involves estrogen signaling." (PMID 36768435, 2023). "High as well as aberrant expression of FBLN1 was assessed in breast carcinoma." (PMID 37719007, 2023). "Besides, FBLN1 is aberrantly expressed in ovarian and breast cancer cells and has been identified as a breast cancer-restricted antigen." (PMID 35127942, 2022). "Consequently, FBLN1 functions as a tumor suppressor in gastric cancer, prostate cancer, breast cancer, and ovarian cancer." (PMID 35127942, 2022). "Because of the scarcity of literature on the role of the ectopic FBLN-1 protein in the growth suppression of breast cancer cells, this subject matter may open up a new direction for cancer research." (PMID 36361532, 2022).
breast carcinoma (continued). "However, Fibulin-1 suppresses doxorubicin-induced apoptosis in breast cancer, implying that the biological role of Fibulin-1 is largely cell context-dependent." (PMID 32612994, 2020). "Fibulin-1 promotes doxorubicin resistance in breast cancer cells." (PMID 31334229, 2019). "In contrast, in the absence of fibulin-1, ADAMTS-1 shows a protumor function, indicating that the fibulin-1/ADAMTS-1 interaction could be considered a good prognostic factor in mammary tumors." (PMID 31508361, 2019). "As to function of these proteins in migration, reduced attachment and decreased migratory speed has been reported for a human breast cancer cell line (MDA MB231) in response to FBLN1 overexpression and siRNA mediated knockdown of FBLN1 in corneal fibroblasts upregulated cell migration." (PMID 29673351, 2018). "Fibulin-1 inhibits in vitro cell adhesion and motility in a cell- and matrix-specific manner; fibronectin is required for fibulin-1 to suppress cell motility of breast cancer and ovarian cancer cells." (PMID 30227601, 2018). "Fibulin 1 may be involved in cell motility and anchorage-independent growth of tumor cells and is overexpressed in breast cancer specimens and breast cancer cell lines." (PMID 24587767, 2014). "As overexpression and abnormal localization in breast cancer can lead to recognition of Fibulin-1 as an autoantigen, its decreased expression in prostate cancers may also lower their immunogenicity." (PMID 17280610, 2007). "Fibulin-1 protein expression was also semiquantitatively assessed by immunoblot analysis in a collection of normal breast tissues (n=18), benign tumours (n=5) and breast carcinomas (n=39)." (PMID 12644824, 2003). "In addition to elevated expression of the full-length (100 kDa) fibulin-1 polypeptide in breast carcinomas vs normal breast tissue, we also observed differential production of additional fibulin-1 immunoreactive fragments." (PMID 12644824, 2003). "Examination of breast carcinomas revealed that the tumour cells also expressed fibulin-1 protein." (PMID 12644824, 2003). "The 55 kDa fragment of fibulin-1 detected in both normal and breast cancer tissues may represent a precursor form, which is further digested to the 50 kDa fragment." (PMID 12644824, 2003). "Interestingly, we found an inverse relation between the levels of full-length fibulin-1 protein and ERα protein concentration in breast cancers." (PMID 12644824, 2003). "Thus, it is unlikely that the increase in the expression of full-length fibulin-1 protein in breast carcinoma is due primarily to an increase in the ratio of epithelial cells." (PMID 12644824, 2003). "Interestingly, Fibulin-1 is increased in ovarian and breast cancers." (PMID 32612994, 2020). "In addition, it has been suggested that AAbs to Fbln-1 may perhaps be exploited as a tool for early detection of breast carcinoma." (PMID 21113302, 2010). "Furthermore, human placenta-derived fibulin-1 protein has also been shown to inhibit cell adhesion, spreading and motility of a range of human tumour cell lines, including those originating from melanoma, epidermoid carcinoma and breast carcinoma." (PMID 12644824, 2003). "Importantly, fibulin 1 may also confer resistance to doxorubicin treatment on breast cancer cells." (PMID 36768435, 2023). "An evaluation of cancer hallmark gene-sets associated with five continuous phenotypes C3, COL11A1, CXCL12, FBLN1, and S100A4 using the aspatial methods including GSEA, LCT, and RF-GSEA on a single cell breast cancer study." (PMID 36998245, 2023). "Then, we identified SLIT3, FBLN-1, and PENK as active protein ligands secreted from CD36+ FBs that induced growth suppression of MDA-MB-231 breast cancer cells and determined their minimum effective concentrations." (PMID 36361532, 2022). "FBLN1, a glycoprotein member of ECM, is epigenetically downregulated in bladder cancer and interacts with ADAMTS to reduce the proliferation of the breast cancer cell lines MCF7 and MDA-MB-231." (PMID 34572749, 2021).
breast carcinoma (continued). "Consequently, both fibulin-1 and -2 may inhibit oncogenic properties of breast cancer cells." (PMID 24457941, 2014). "Among them, FBLN1 and FBLN2 (fibulin 2) were found to be downregulated and acted as tumour suppressive genes in certain cancers such as prostate cancer and breast cancer." (PMID 18985039, 2008). "Similarly, breast cancer patients with increased PXDNL (p=0.00011) and SDC1 (p<0.0001), and decreased FBLN1 (p=0.033) and ADAMTS8 (p=0.00017) expression levels tended to have shorter disease-specific survival (DSS) time." (PMID 37056938, 2023). "For example, fibulin-1 maturation and mislocalisation have been found in breast cancer, while in prostate cancer, fibulin-1 was also down-regulated but did not induce by 5-aza-2′-deoxycytidine." (PMID 25234557, 2014). "When viewed as the ratio of the 50 kDa fragment to the mature fibulin-1 polypeptide, fibulin-1 processing was more extensive in ERα-positive as compared to ERα-negative breast carcinomas (P < 0.05, n=36)." (PMID 12644824, 2003). "Consequently, the simultaneous presence of fibulin-1 and ADAMTS-1 or of fibulin-2 and ADAMTS-12 could be considered a good prognostic factor in breast cancer." (PMID 31508361, 2019). "Moreover, an increased ratio of the 50 kDa fragment to the mature fibulin-1 polypeptide was observed in ERα-positive breast carcinomas as compared to ERα-negative carcinomas." (PMID 12644824, 2003).